CRP (C-reactive protein)
Diseases named in the same sentence as CRP in open-access papers (continued):
Sharing a sentence is not in itself a finding about the gene and the disease.
Obesity (continued). "Indeed, higher RBC LC-PUFA among Yu’pik Peoples in Alaska attenuates the positive relationship between obesity and CRP concentrations." (PMID 23547888, 2013). "However, it is important to note that BMI also affects WBC count, with obesity creating a proinflammatory state characterized by increases in C reactive protein and interleukin 6 concentrations as well as in WBC count." (PMID 22613769, 2012). "Some authors have shown that smoking, obesity or trauma may affect CRP values and we also have to keep in mind that vascular alteration in diabetic patients are inflammatory processes that could increase blood inflammatory mediators." (PMID 22322513, 2012). "An alternative explanation is that obesity upregulates the production of both leptin and a cytokine regulating CRP synthesis without a causal relationship between leptin and CRP." (PMID 22533665, 2012). "However, both poor CRF (OR 2.7, 95% CI: 1.2–6.1, p = 0.02) and overweight/obesity (BMI ≥ 85th percentile) (OR 2.5, 95% CI: 1.1–5.9, p = 0.03) were independent predictors of elevated salivary CRP secretion rates (≥ 75th percentile, ≥ 1276.39 pg/ml)." (PMID 23108518, 2012). "Consistent with our findings, Fischer and colleagues showed that the plasma levels of CRP were associated with physical inactivity, independent of obesity." (PMID 22524121, 2012). "The likely explanation regarding hs-CRP could be related to genetic variations of CRP genes and stimulants (such as obesity and low levels of physical activity) which may require different mechanisms." (PMID 23283045, 2012). "After adjusting for potential mediators oral hygiene plus C-reactive protein (data not shown), the magnitude of association with obesity decreased by 47% [OR (obese × 2 or more teeth) 1.38 (95% CI: 0.68, 2.80)]." (PMID 22671969, 2012). "A limitation of our study may be the decision to measure CRP at diagnosis, which may have obscured the contribution from obesity, as inflammation within the primary tumour may have been the main contributor to high serum CRP." (PMID 21081932, 2011). "The strong positive association between amylin and the risk of MetS was independent of the well established risk factors, including obesity, inflammatory markers (CRP and IL-6) and insulin resistance in apparently healthy Chinese population." (PMID 21935471, 2011). "Even thought that IL-6 is closely associated with TNF-α in exercise, in the present work we chose CRPhs as marker of chronic low-grade inflammation, because CRP is positively correlated with obesity, insulin resistance and has been shown to better predict CVD than other cytokines." (PMID 22174491, 2011). "Associations between CRP and other surrogate markers of obesity were not significant in this study, although this link is supported in the literature." (PMID 21081932, 2011). "Obesity is associated with "low-grade inflammation", a term that is used to reflect increments in the systemic concentration of tumour necrosis factor-alpha (TNF-α), interleukin (IL)-1β, IL-6, IL-1ra, and C-reactive protein (CRP)." (PMID 21599899, 2011). "Indeed, CRP increases in other conditions, such as inflammation, obesity, and cardiovascular disease; however, it is also a elevated AFL-induced protein in rats as discovered in this study." (PMID 21806828, 2011). "This does not; however, appear to be the case for non-obesity cardiometabolic risk factors such as C-reactive protein, blood pressure, and non-HDL." (PMID 21998688, 2011). "Together with our data, this suggests that CRP from inflammation in advanced cancer may obscure that from obesity-related inflammation." (PMID 21081932, 2011). "The following were risk factors of ICU admission: older age (p = 0.03), long duration of symptoms (p = 0.07), asthma (p = 0.01), obesity (P < 0.001), abnormalities of chest radiography (P < 0.001), leukocytosis (p = 0.005), and higher C-reactive protein (CRP) (P < 0.001)." (PMID 20979619, 2010).
Obesity (continued). "On factor analysis, both CRP and fibrinogen clustered with obesity in women (this factor explained 20% of variance); but in men, CRP clustered with obesity (factor explained 18% of variance) whilst fibrinogen clustered with HbA1c and urine ACR (factor explained 13% of variance)." (PMID 21029470, 2010). "CRP is now considered a key marker for low-grade systemic inflammation which, in turn, is considered by leading scientists to be responsible for a number of metabolic problems that result in unwanted weight gain and obesity." (PMID 20170522, 2010). "Other risk factors like family history of premature CV disease, obesity, high sensitivity CRP, inflammatory cytokines and lifestyle are not incorporated in present risk formulae." (PMID 20500815, 2010). "Moreover, using high-sensitivity assays for CRP (hs-CRP), several studies have shown elevated CRP levels in obesity, since adiposity resembles a low grade systemic inflammatory state and hs-CRP is released by adipose tissue." (PMID 20614004, 2010). "Obesity stimulates CRP synthesis mainly due to circulating levels of IL-6." (PMID 20646281, 2010). "This is supported by clinical and epidemiological studies showing larger venular caliber to be associated with systemic biomarkers of inflammation, including C-reactive protein and interleukin-6, and with impaired fasting glucose metabolism, dyslipidemia, obesity and cigarette smoking." (PMID 21060863, 2010). "Several studies showed that the association of CRP with insulin resistance was independent of obesity." (PMID 21167068, 2010). "Furthermore, obesity also increases serum C-reactive protein and ferritin concentrations pointing to the existence of chronic inflammation and increased body iron stores in obesity and other disorders characterized by the presence of insulin resistance." (PMID 19440331, 2009). "Evidence supports an inverse association between physical fitness and various CVD risk factors, including glucose tolerance, cholesterol, blood pressure, resting pulse rate and obesity, and markers of systemic inflammation including C-reactive protein (CRP), and TNFα." (PMID 18307781, 2008). "CRP haplotypes were not, however, associated with risk factors, such as high blood pressure, dyslipidaemia, obesity, physical inactivity and low socioeconomic position (1 of 36 tests statistically significant at p<0.05; 1–2 would have been expected by chance)." (PMID 18714381, 2008). "The link between obesity and inflammation has been further illustrated by the increased plasma levels ofseveral proinflammatory markers including cytokines and acutephase proteins like C-reactive protein (CRP) in obese individuals." (PMID 17389767, 2007). "The poorer response to urticaria treatment at this age in our study could be attributed to the higher occurrence of depression, autoimmunity, systemic inflammation (increased CRP levels), obesity and comorbid CIndU or the higher frequency of Type IIb autoimmune endotype in females." (PMID 40965122, 2026). "Similarly, SHBG, A2M and CRP all showed obesity-dependent levels." (PMID 39972214, 2025). "We hypothesised that body mass index (BMI)-driven CRP would comparably associate with an increase in complement proteins when obesity was accounted for in non-obese women with and without PCOS." (PMID 40243681, 2025). "Notably, one study demonstrated that weight loss led to reductions in IL-6, IL-1 receptor antagonist, and CRP, suggesting that obesity-related inflammation may be at least partially reversible." (PMID 40722634, 2025). "Some evidence suggests that CRP itself may participate in signaling pathways responsible for musculoskeletal pain sensation and activation, potentially representing another mechanism through which obesity exacerbates LBP." (PMID 40507523, 2025).
Obesity (continued). "During the first trimester, hs‐CRP compared to those of normal‐weight individuals (mean 3.4 mg/L; 95% CI 3.1 to 3.7) showed a 1.7‐fold increase in overweight (mean 5.9 mg/L; 95% CI 5.0 to 6.7; p < 0.0001) and a 2.7‐fold increase in obesity (mean 9.3 mg/L; 95% CI 7.6 to 11.0; p < 0.0001)." (PMID 40329709, 2025). "However, the same dose of 1 g/day of ginger rhizome powder, when administered to children with obesity, led to significant reductions in serum fasting blood sugar, CRP, body mass index (BMI), waist circumference, waist-to-height ratio, alanine aminotransferase, TC, and LDL-C." (PMID 40733199, 2025). "Obesity, particularly visceral obesity, has a significant impact on periodontitis through various mechanisms, including systemic inflammatory responses, alterations in the oral microbiome, elevated C-reactive protein levels, increased free fatty acids, insulin resistance, and oxidative stress." (PMID 40499289, 2025). "Additionally, the chronic low-grade inflammation in obesity, characterized by an increase in pro-inflammatory cytokines such as IL-6) and tumor necrosis factor-α, along with C-reactive protein, creates a state that may precipitate insulin resistance." (PMID 39996060, 2025). "In the context of obesity and insulin resistance, its clinical utility lies in detecting low-grade metabolic inflammation arising from excess adipose tissue—particularly visceral adiposity—through sustained cytokine release (e.g., IL-6) that stimulates hepatic CRP synthesis." (PMID 41305609, 2025). "CRP is an acute inflammatory protein synthesized in hepatocytes under the primary stimulus of IL-6, reflecting systemic inflammation, which is a component of the state of obesity, T2DM, and atherosclerosis, likely due to cytokine stimulation by adipose tissue, among others." (PMID 40244195, 2025). "Moreover, the association between carnitine and obesity may also involve pathways of oxidative stress (e.g., inhibition of NF-κB expression) and chronic low-grade inflammation (e.g., decreased levels of IL-6, TNF-α, and CRP), which are hallmarks of obesity." (PMID 41291687, 2025). "Data from the National Health and Nutrition Examination Survey (NHANES) show that mean CRP levels in adults with obesity can exceed 5 mg/L, while in the population with overweight, values typically range between 2 and 3 mg/L, indicating a nearly two-fold increase in systemic inflammation in obesity." (PMID 40868054, 2025). "Also, it may be that smoking and/or obesity contribute to an elevated CRP which, being a component of the ASDAS, influences the treatment response measures." (PMID 40646655, 2025). "Obesity further contributes to systemic low-grade inflammation, especially via visceral fat accumulation and metabolic dysfunction, leading to increased levels of IL-6, C-reactive protein, and tumor necrosis factor-α (TNF-α), which can trigger or worsen airway hyperresponsiveness." (PMID 40933690, 2025). "Obesity is associated with chronic low-grade inflammation, which can promote carcinogenesis as excess adipose tissue leads to the secretion of inflammation-related macrophages and adipokines such as interleukin (IL)-6, plasminogen activator inhibitor-1 (PAI-1), and C-reactive protein (CRP)." (PMID 40722646, 2025). "In the elderly DFI population, the quantitative serum CRP level is dynamic and influenced by many inherent co-morbidities such as gout, cancer, rheumatic diseases, thrombosis, statin drugs, Charcot foot arthropathy, hematoma, ischemia, dialysis, cirrhosis, trauma, obesity, or being postoperative." (PMID 40565868, 2025). "We did not collect data on inflammatory biomarkers such as C Reactive Protein, IL-6, or adipokines, despite increasing evidence that chronic low-grade inflammation plays a key role in the metabolic and cardiovascular risks associated with obesity." (PMID 41010615, 2025). "MPO and CRP may contribute to impaired microvascular function in obesity." (PMID 40900465, 2025).
Obesity (continued). "Additionally, obesity itself is currently recognized as a potential risk factor for IBS, with clinical studies finding a positive correlation between body mass index and the levels of complement C3 and C-reactive protein in IBS patients." (PMID 40797420, 2025). "Some research conveyed that obesity could lead to a proinflammatory environment dominated by high levels of C-reactive protein, interleukin-6, and tumor necrosis factor-α, as well as a relative deficiency of protective immune cell types in the endometrium, which may contribute to EC risk." (PMID 40538813, 2025). "Obesity is associated with the presence of prothrombotic factors (e.g., fibrinogen, homocysteine), inflammatory markers (e.g., interleukin-6 (IL-6), tumor necrosis factor-alpha (TNF-α), C-reactive protein (CRP)), and adipocytokines (e.g., leptin, adiponectin))." (PMID 39857920, 2025). "We conducted a comprehensive comparison of the diagnostic value of traditional inflammatory biomarkers (CRP and ESR), fibrinolytic biomarkers (fibrinogen and D-dimer), and previously established biomarkers (CAR, CLR, and CMR) in PJI patients, considering their obesity status." (PMID 40041151, 2025). "The well-known link between obesity and systemic inflammation in adults seems to also apply to childhood obesity with increased levels of pro-inflammatory cytokines and adipokines as well as elevated C-reactive protein (CRP) measured in the blood of children with obesity as young as age 3 years." (PMID 38680993, 2024). "In a cohort of 5- to 9-year-old prepubertal children with overweight and obesity, we observed early insulin resistance driven by high insulin levels, as fasting glucose levels remained normal, and elevated markers of inflammation including CRP and the leptin/adiponectin ratio." (PMID 38680993, 2024). "Based on the available data, our network meta-analysis concludes that EHDS may be the optimal dosing strategy for vitamin D supplementation to reduce the inflammatory response (CRP) and improve insulin resistance in children and adolescents with overweight/obesity." (PMID 38160221, 2024). "In addition, considering that the metabolic syndrome caused by obesity is caused by inflammation secreted by fat tissues, the increase in HDL, LDL, and CRP in this study indicates that exercise lowers the chain reaction of body fat-abnormal lipidemia-inflammation." (PMID 38684812, 2024). "In a meta-analysis of 48 prospective non-randomized studies, the authors reported that BS decreases the low-grade inflammation associated with obesity as measured by C-reactive protein (CRP) and interleukin 6, but not by tumor necrosis factor α, after pooling groups at 6 and 12 months follow-up." (PMID 39574780, 2024). "C-reactive protein (CRP), adipocyte-derived metabolites, and inflammatory cytokines [such as tumor necrosis factor alpha (TNF-α), IL-1β, and IL-6] have been shown to play a role in inflammation associated with obesity, and in the development of insulin resistance." (PMID 38978699, 2024). "Another possibility is that rice and meat pattern may increase obesity risk in children through lipid metabolism pathways, rather than the CRP pathway." (PMID 39599620, 2024). "Furthermore, findings also suggest that routine laboratory parameters, such as total leukocyte/white blood cell (WBC) count and C-reactive protein (CRP), may serve as reliable markers of inflammation in children and adolescents with obesity." (PMID 39857642, 2024). "In the BMI stratified analyses, we observed an association between high CRP and inferior DFS in patients with normal-weight, overweight, and obesity, although less evident among patients with obesity, which may be explained by low numbers of patients with obesity." (PMID 38914635, 2024).
Obesity (continued). "Laurate-bioconjugated fructans could be useful to counteract the adverse effects of a high-fat diet on the characteristics of MetS such as obesity, insulin resistance, high blood pressure, and hypertriglyceridemia, probably by decreasing food intake and modulating CRP and IL-10." (PMID 39204141, 2024). "This led to the hypothesis that non-infectious conditions, such as cancer, obesity, trauma, or surgery, might elevate CRP levels and thus act as PE risk factors." (PMID 39458053, 2024). "CRP in chronic inflammatory conditions of obesity can also damage the function of BBB and increase BBB permeability, resulting in reactive glial proliferation and affecting central nervous system function, which may be a major factor of central leptin resistance in chronic inflammation." (PMID 37660067, 2023). "Obesity has been shown to contribute to a pro-inflammatory state, where activated mononuclear cells produce pro-inflammatory cytokines, while excess adipose tissue is believed to induce production of inflammatory cytokines and increased levels of C-reactive protein (CRP)." (PMID 37692782, 2023). "However, since both CRP and obesity in this study were assessed at the same point in time, temporality could not be inferred, and domain-specific associations were not examined." (PMID 36462595, 2023). "Elevated level of the C-reactive protein (CRP) has been reported in obese patients with periodontitis while overexpression of VEGF has been observed in inflamed periodontal tissues of patients with type 2 diabetes, another chronic inflammatory disease often associated with obesity." (PMID 37384642, 2023). "As the TBF percentage (severity of obesity) increases, CD4+, CD4+CD62-, and CD8+CD45RO+ T lymphocytes increase in peripheral blood, demonstrating the existence of an inflammatory process at the peripheral level that is also associated with other variables such as WC, BMI, CRP, leukocytes, and age." (PMID 37334132, 2023). "CRP genetic knock out animal studies have shown that absent CRP, models of autoimmune arthritis, atherosclerosis, response to toxins, obesity and insulin resistance have all implicated CRP as an active regulator of the innate immune system rather than being a passive marker of inflammation." (PMID 37048104, 2023). "Given these relationships, and as obesity relates to greater insulin resistance, inflammation, type 2 diabetes, and other cardiovascular diseases, adolescents with OWOB present as a high-risk group for a range of adverse physical health outcomes during the pandemic, including elevated CRP levels." (PMID 38136035, 2023). "Moreover, CRP impairs insulin receptor substrate 1 (IRS-1) which might explain the state of insulin resistance in obesity due to elevated CRP levels." (PMID 36520252, 2023). "Recent evidences suggested that overweight and obesity may be characterized by a low-grade chronic inflammatory state, as reflected by elevated levels in inflammatory mediator such as high sensitivity C-reactive protein (CRP)." (PMID 37670381, 2023). "C reactive protein is associated only with obesity, not with the metabolic syndrome." (PMID 36981858, 2023). "Regarding the effects of zinc on obesity-related inflammation and its complications, zinc supplementation combined or not with restricted caloric diets has showed to modify inflammatory markers, reducing the levels of IL-6 and C-reactive protein (CRP) in obese individuals." (PMID 38260166, 2023). "In addition to finding correlations between obesity and the salivary measures of insulin, CRP, and adiponectin, the progressive nature of their suggested scoring system, as opposed to the binary definition of the disease in adults, revealed a higher level of sensitivity for pediatric populations." (PMID 36831972, 2023).